KRAS (KRas proto-oncogene, GTPase)
Diseases named in the same sentence as KRAS in open-access papers (continued):
Sharing a sentence is not in itself a finding about the gene and the disease.
tumor (continued). "Reversing this process by targeting the oncogenic miRNAs (miR-25-3p and/or miR-15a-5p) and modulating the ratio between the tumor-suppressor miRNA (miR-18a-3p) and its downstream target (KRAS) has direct effect on proliferation and survival." (PMID 28904816, 2017). "Direct targeting of HK2 can, therefore, impede the flow of glucose into multiple downstream pathways necessary for KRAS driven tumor growth." (PMID 28915575, 2017). "Of note, especially in the case of rectal cancer, the tumor material available to laboratories for testing may be limited to only small biopsies, or tissues from partially treated patients containing only few cancer cells, thus making KRAS mutational assessment even more challenging." (PMID 28636636, 2017). "In univariate analyses, five variables, including KRAS mutation, Fong CRS > 2, tumor number>1, size > 5 cm at diagnosis, and poor response to preoperative chemotherapy, were associated with decreased OS (p < 0.050)." (PMID 29108374, 2017). "We further demonstrated that this pathology-determined OS can be affected by both tumor stage and status of oncogenic mutations in EGFR, KRAS, ALK, RET, and BRAF genes." (PMID 29137260, 2017). "Wild-type KRAS was detected in eight of 11 samples, while mutant KRAS was detected in three primary tumor samples." (PMID 28468669, 2017). "The most significant signalling hallmarks and genes enriched in the gene set enrichment analysis for the paeditatric tumours analysed here, was KRAS and KRAS signalling pathway." (PMID 28969007, 2017). "Only three patients had KRAS, NRAS or BRAF mutations, which we were able to follow in cfDNA and BM-derived tumour DNA during the course of trametinib therapy to evaluate the subclonal response to treatment." (PMID 28492226, 2017). "Like KRAS testing, MSI testing was associated in multivariate analysis with young age, higher tumor stage and geographical area of primary treatment." (PMID 29137623, 2017). "In detail, KRAS wildtype patients with right sided tumor location had a 25% lower ORR than those with left sided tumors in the first line of palliative chemotherapy." (PMID 29221186, 2017). "The tumor-stroma interface provided another demonstration of probe specificity: for example, in a KRAS G12D homozygous mutant tumor, positive signal from the KRAS wild-type probe was only evident in stromal cells." (PMID 29222441, 2017). "Again, a recent study on both cell lines and tumor specimens highlighted the importance of NGS in detecting genes potentially involved in the resistance to anti-EGFR therapy in KRAS wild-type patients." (PMID 29221448, 2017). "BxPc3 and PaCaDD 165, which have a low GPRC5A mRNA and protein level, show both a KRAS wild type indicating that RAI3 expression increases with malignancy of a tumor." (PMID 28114355, 2017). "The inhibitory effect of the 6F6 mAb on tumor growth was confirmed in mice xenografted with DiFi CRC cells (wild type KRAS) that overexpress CLDN1 (p = 0.03)." (PMID 28659146, 2017). "Taken together, dPCR was able to more thoroughly identify the true mutational status of the KRAS gene in PDAC patients compared to Sanger sequencing, even from limited tumor tissues available from FFPE pancreas EUS-FNA biopsy specimens." (PMID 28125707, 2017). "Using the system, we detected CTC heterozygosity and heterogeneity in KRAS status among CTCs within a patient and between CTCs and tumor tissues." (PMID 28468669, 2017).
tumor (continued). "Response profiles to cetuximab showed distinctive signatures segregating strong responders from resistant tumours, showing also a third group of PDXs displaying moderate/minor responders that included KRAS mutants." (PMID 28186126, 2017). "In a cohort of patients whose archival tumor was KRAS WT and consequently received anti‐EGFR therapy, KRAS mutations were detected by BEAMing in the plasma of 48% of patients at disease progression." (PMID 28106345, 2017). "The only neoantigen identified in more than one tumor was KRAS G12C, which produces a neoantigen for a single HLA type (HLA-A*11:01; US population frequency = 10.4%)." (PMID 28231819, 2017). "There are significant differences among the subtypes in tumor location (P<0.01), proportion of MSI-H tumors (P<0.001), presence of mucin (P<0.001), and incidence of KRAS mutation (P<0.05)." (PMID 28455965, 2017). "The majority of previous studies investigating the concordance of the mutational profile of metastatic sites with that of the primary tumour focused on a limited number of genes (e.g. KRAS)." (PMID 29029407, 2017). "This study generally found this to be true, with both CIMP-H tumours being located in the right colon and having BRAF mutations and KRAS wild type." (PMID 28097409, 2017). "Of interest, in 2 patients tumor tissue genotyping for KRAS revealed a wild type situation, while the respective baseline cfDNA harbored KRAS mutations." (PMID 28328955, 2017). "In June 2013, EU treatment guidelines changed to recommend that panitumumab should be prescribed to patients with mCRC and wild-type RAS tumour status (exons 2, 3, 4 of KRAS and NRAS), which should be confirmed prior to treatment initiation." (PMID 29183279, 2017). "We analyzed seven blind coded clinical FFPE tumor samples for which sanger sequencing data of the KRAS status was available." (PMID 28542229, 2017). "We found that Selumetinib induced a significant reduction in proliferation specifically in KRAS (codon 12 and 13) mutant tumours." (PMID 28931905, 2017). "The KRAS peptide vaccine exhibited striking efficacy, reducing tumor number and tumor burden by >80% when compared with adjuvant alone." (PMID 29137294, 2017). "Among CRC patients with mutated RAS tumours (37/88; 42.0%), four tumours would have been classed as wild-type RAS using conventional diagnostics: two had NRAS codon 61 mutations and two had KRAS codon 146 mutations (outside the scope of the cobas assay)." (PMID 28196074, 2017). "Since FOXM1 is required for KRAS/ERK signaling in mouse tumor models, our studies provide a rationale for pharmacological targeting FOXM1 in PIMA tumors with activating KRAS mutations." (PMID 29267283, 2017). "It is of note that of the 21 patients with KRAS mutations in the CTC and the primary tumor, only 58% had a matching mutation in CTC and tissue." (PMID 28674438, 2017). "For example, MicroRNA-30b can function as a tumor suppressor in CRC by targeting KRAS, PIK3CD and BCL2, while MicroRNA-224, a tumor promoter, targets PHLPP1 and PHLPP2, sustains Wnt/β-catenin signaling and promotes aggressive phenotype of CRC." (PMID 29118671, 2017). "This would lead to detection of circulating mutant KRAS as tumor burden increased and all cells increased in number including those harboring wild-type or mutant-KRAS." (PMID 28981524, 2017). "SB favors the development and progression of pancreatic neoplasia compared to KRAS alone and allows one to explore all the stages of tumor development." (PMID 29156578, 2017).
tumor (continued). "Tumor samples underwent routine pathology examination including evaluation for tumor budding and KRAS." (PMID 28863773, 2017). "Among metastatic CRCs, age (<60 years), site of primary tumour (left colon) and geographical area of treatment were factors related to KRAS testing." (PMID 29137623, 2017). "The TCGA dataset included 37 normal mucosa samples and 203 tumor samples, 25 of which carry a BRAF mutation and 81 a KRAS mutation." (PMID 28931069, 2017). "In 10 of 11 (90.9%) cases, the KRAS status of the primary tumor matched that of CTCs by either direct PCR or WGA methods." (PMID 28468669, 2017). "Much work has focused on identifying additional pathways promoting KRAS driven tumor growth in PDAC, with the hope of identifying new targets for therapy." (PMID 28915575, 2017). "KRAS mutations in CTC and corresponding tumor were discordant in 11 of 26 “tumor-CTC-pairs” (42%), while 15 (58%) had a matching mutation; survival was similar in both groups (P = 0.36)." (PMID 28674438, 2017). "Better knowledge of tumor biology, especially of specific molecular alterations such as mutations of the epidermal growth factor receptor (EGFR) and the KRAS gene led to the discovery of the biomarkers used as target therapies." (PMID 29285236, 2017). "An intriguing report documented loss of heterozygosity (LOH) at the HLA locus, with loss of HLA-C∗08:02 in the resistant lesion from a tumor treated with tumor-infiltrating lymphocytes composed of T cell clones targeting KRAS G12D." (PMID 29107330, 2017). "Among the 160 patients with known KRAS mutations in the resected CRC tissue, we detected tumor-specific KRAS mutations in the plasma of 39.6% (42/106) of metastasis group and 5.6% (3/54) of the non-metastasis group." (PMID 28459822, 2017). "There were statistically significant associations between pre-treatment plasma TIMP-1 and WHO performance status (PS), location of the primary tumor, previous adjuvant chemotherapy, KRAS and BRAF status." (PMID 27509063, 2016). "Clinical outcome was better in patients with KRAS exon 2 wild type compared with KRAS exon 2 mutant tumours." (PMID 26766738, 2016). "We identified the tumor suppressive miRNA, miR-185, to interact with the KRAS 3′ UTR via a 49-nt fragment and possibly via other regions as well, such as one miR-185 binding site about 500 bp away from the end of the 3′ UTR predicted by TargetScan." (PMID 26930719, 2016). "Three tumors (cases 2, 7, 12) presented KRAS12−13 PLLM or MUT in at least one of the tumor areas selected, but they also presented other KRAS or NRAS MUT or PLLM in other areas of the tumor (case 2) or in the same area (case 7, 12)." (PMID 27916952, 2016). "Almost all received prior oxaliplatin and irinotecan (99 %), 92 % had prior bevacizumab, and 283/291 (97 %) of patients with KRAS wild-type tumours had previously received anti-EGFR therapy." (PMID 27389564, 2016). "Other studies revealed that the star strand of mir-18a and miR-4689 function as potential tumor suppressors by targeting KRAS." (PMID 26623728, 2016). "Three members of the GTPases of the RAS family, KRAS, HRAS and NRAS, are well known for their ability to cause neoplasia." (PMID 27857191, 2016). "One tumor exhibited high-level amplification of a component with two low-level amplifications (high FGFR2/low KRAS and EGFR amplification in one case)." (PMID 27014419, 2016).
tumor (continued). "As a complementary approach, synthetic lethal chemical screening opens a new avenue for the therapeutic treatment of KRAS-transformed tumours." (PMID 27193833, 2016). "After expression and purification of the rest of the recombinant chimeric proteins, we examined their abilities to induce cell death in several mutant KRAS-expressing tumor cell lines." (PMID 27322423, 2016). "Tumors with specific genetic alterations, such as KRAS or EGFR mutations, were also distinguished and the location of the primary tumor identified with 71% accuracy." (PMID 28066769, 2016). "We demonstrated that plasma EGFR and KRAS mutation testing using PNA-based real-time PCR methods is feasible and can be applied as an alternative to tumor genotyping when deciding upon the optimal treatment of NSCLC patients." (PMID 27519791, 2016). "Phosphoprotein activation of several MAPK signaling components frequently is stronger in KRAS-mutants than in any other tumor groups." (PMID 27632281, 2016). "The objective of this study was to compare the plasma analysis performed using PANAMutyperTM R EGFR and KRAS kits with tumor tissue analysis performed using routine EGFR and KRAS mutation tests." (PMID 27519791, 2016). "Recently, determination of KRAS was performed in circulating tumour cells (CTCs) or in plasma circulating DNA (ctDNA) to determine PDAC prognosis; the results of this study have confirmed the utility of liquid biopsy as a promising material for diagnosis." (PMID 27689078, 2016). "We synthesized a targeted TBN as an effective siRNA delivery system to sensitize the KRAS mutant tumor cells to gefitinib." (PMID 27530552, 2016). "We show that expression and activation of either ChR2D156A, a blue-light activated cation channel, or Arch, a green-light activated proton pump, both of which hyperpolarize cells, significantly lowers the incidence of KRAS tumor formation." (PMID 26988909, 2016). "As its inactivation leads to tumour regression, mutant KRAS is considered an attractive target for anticancer drugs." (PMID 27929127, 2016). "For instance, when considering CNIs as a targeted therapeutic agent for KRAS-mutated CRC, the impact of immunosuppression on tumor development should be considered." (PMID 27526107, 2016). "These include the use of monoclonal antibodies against the epidermal growth factor receptor (EGFR) in patients with KRAS wild‐type (WT) tumours, although only a minority of patients respond to this approach." (PMID 26690310, 2016). "One of the main findings of the current study was that inhibiting CXCR2 genetically or pharmacologically decreased KRAS(G12D)-induced tumor cell growth." (PMID 26771140, 2016). "For mutational profiling, KRAS, BRAF, and PIK3CA hotspot mutations were analyzed in CTCs and ctDNA from 23 samples, nine matched liver metastases and three primary tumor samples." (PMID 27863403, 2016). "Here, we describe a series of experiments aimed at identifying novel dependencies in KRAS mutant tumour cells." (PMID 26881434, 2016). "MiR-206 directly targeted KRAS, thereby acting as tumor suppressor in PDAC cells by blocking cell cycle progression, cell proliferation, migration, and invasion." (PMID 26646588, 2016). "Tumor EGFR mutation, KRAS mutation and ALK rearrangement status were available for 124 (72.5 %), 126 (74 %), and 167 (98 %) patients, respectively." (PMID 27422280, 2016).
tumor (continued). "At the time of diagnosis, the tumor cells had four distinct SNVs in USP54, GABRA3, KRAS and SETD2, while the relapsed tumor acquired four additional unique mutations in MYH7, NYNRIN, ODZ1 and ZIC3." (PMID 26527318, 2016). "A time course analysis showed that, in KRAS-induced ascites, the proportion of neutrophils gradually increased from the early point of tumor progression." (PMID 27483433, 2016). "A Cox proportional hazard model was built to predict survival, adjusted for clinicopathological characteristics and tumor molecular features, including the CpG island methylator phenotype (CIMP), microsatellite instability (MSI), and KRAS mutations." (PMID 27643594, 2016). "The cell proliferation rate, which was measured by the percentage of Ki-67-positive tumor cells, was decreased in the group implanted with the miR-16 lentivirus and increased in the group treated with the KRAS plasmid." (PMID 27857191, 2016). "PCR-based sequencing for hot spot mutations of KRAS, BRAF and PIK3CA genes in CTCs revealed similar mutations as tumor biopsies for 77.8% of the patient samples." (PMID 27863403, 2016). "At the same time, the three tumor types showed a significantly different distribution of KRAS substitutions (P ≪ 0.001 for all comparisons)." (PMID 26902163, 2016). "In this study, we found that the expression levels of KRAS were significantly higher in CRC clinical tissues than in the non-tumor adjacent tissues." (PMID 27857191, 2016). "HER2‐overexpression was associated with KRAS/BRAF wild‐type (WT) status at all stages: in 5.2% WT versus 1.0% mutated tumours (p < 0.0001) in stage IV and 2.1% versus 0.2% in stage II–III tumours (p = 0.01), respectively." (PMID 26690310, 2016). "Patients, divided into groups on the basis of marker cut-offs, were all comparable for age, gender, tumor localization, CT regimen, KRAS status and treatment arm." (PMID 27120807, 2016). "In another report, knock-down of KRAS(G12D) in a tumor derived cell line SW1990 down-regulated the transcripts of CXCR2 ligands." (PMID 26771140, 2016). "By comparing immunohistochemical scores of tumor samples with high or low bacteria abundance, we observed that KRAS was highly expressed in F.nucleatm high abundance group, B. fragilis high abundance group and F. prausnitzii low abundance group." (PMID 27323816, 2016). "KRAS and PIK3CA mutation frequently coexist, with activation of parallel pathways in a single tumour." (PMID 27340376, 2016). "KRAS mutations in CRC lead to a decrease in RCAN2 expression, resulting in tumor proliferation due to derepression of calcineurin–nuclear factor of activated T cells (NFAT) signaling." (PMID 27526107, 2016). "Knocking-down CXCR2 in KRAS(G12D)-bearing human pancreatic duct-derived cells demonstrated a significant decrease in the in vitro and in vivo tumor cell proliferation." (PMID 26771140, 2016). "Provided the relatively low incidence of the single gene mutations, clonal mutations (detected in >20% of tumor population) were grouped into the JAK/STAT (IL7R, JAK2, JAK1, CRLF2 mutations and CRLF2-rearrangements) and RAS/RTK (FLT3, KRAS, NRAS) pathways." (PMID 26883104, 2016). "We performed pairwise analysis of the three tumor subsets: KRAS mutants, other RTK/RAF/MAPK mutants, and all others." (PMID 27301828, 2016). "Only in a single patient we found discordant results for KRAS testing in two different biopsies from the same tumor analyzed by the SNaPshotTM assay." (PMID 27064574, 2016).